MR1 (major histocompatibility complex, class I-related)
Diseases named in the same sentence as MR1 in open-access papers (continued):
Sharing a sentence is not in itself a finding about the gene and the disease.
tumor (continued). "This review addresses the potential role of MR1-restricted T cells in controlling tumor cells, facilitating their elimination and regulating cancer immunity." (PMID 32411144, 2020). "There is also evidence that tumor-related antigens exist that can bind to MR1 and active MAIT cells, although the specific antigens from tumors are yet to be identified." (PMID 33185693, 2020). "In these models, MAIT cells activated in vivo by MR1-expressing tumor cells suppressed NK cells effector functions, chiefly through IL-17A secretion." (PMID 32411144, 2020). "In this study MAIT cells promoted tumor growth and metastasis by blocking the effector function of NK cells and the therapeutic blockade of MR1 suppressed tumor growth and increased the immune cell infiltration in the tumor and their function." (PMID 33680931, 2020). "MAIT cell activation was blocked by treatment of tumor cells with 6-FP or administration of MR1 blocking antibodies, suggesting TCR-mediated activation of MAIT cells." (PMID 32411144, 2020). "More recently, a diverse, self-reactive, TCR αβ T cell population was identified which was MR1-restricted and exhibited anti-tumor responses." (PMID 32411144, 2020). "There is also evidence that non–riboflavin-based antigens, also of microbial origin and tumor cell–derived molecules, can bind to MR1 and activate some MR1-restricted T cells, although the identity of these antigens remains to be defined." (PMID 33013888, 2020). "Perhaps the inflammatory milieu of the tumor is enriched in factors that increase MR1 expression in tumor tissues, including both tumor cells and stromal cells." (PMID 32756356, 2020). "Clone MC.7.G5 expresses TCRs capable of recognizing MR1-metabolite complexes in the plasma membrane of several different types of tumor cell lines and primary tumor cells in vitro." (PMID 32756356, 2020). "Second, a monoclonal antibody is developed to bind both MR1 and its tumor-specific antigens to induce antibody-dependent cytotoxicity." (PMID 32756356, 2020). "All these potential therapeutic approaches are dependent on MR1 expressed on the tumor cell surface and bound to the cancer-specific metabolites (i.e., neoantigens) but independent of antigen-presenting cell processing." (PMID 32756356, 2020). "The anti-tumor potential of MR1-restricted αβ-TCR T cells is just emerging, and yet to be characterized." (PMID 32570906, 2020). "More recently, tumor-specific activity of an MR1-restricted TCR has been reported with activity against a wide variety of tumors, but not normal tissues or pathogen-derived antigens." (PMID 32570906, 2020). "Degranulation was reduced by >30% when blocking antibodies to MR1 were added to the tumor-derived cultures, showing that cognate antigen recognition partly contributes to MAIT cell degranulation." (PMID 31073372, 2019). "The fact that these cells preferentially recognize tumor cells will promote new studies in patients harboring tumors expressing MR1 molecules." (PMID 29963057, 2018). "In biodistribution studies using athymic nude mice bearing subcutaneous EGFRvIII-expressing U87 tumor xenografts, an up to 244 ± 77% increase in tumor uptake for MR1-1(Fv)-PE38 was observed compared with that for MR1(Fv)-PE38." (PMID 28752098, 2017). "In rat models of GBM, MR1-1(Fv)-PE38, when delivered directly to tumor tissue, displayed a 3.5-fold increased potency towards cells expressing EGFRvIII, compared to MR1(Fv)-PE38." (PMID 28752098, 2017). "Next, we sought to combat T-cell recruitment at the initial time of implantation of human tumor cells by co-administrating the immune checkpoint blockers Abatacept and MR1." (PMID 28977847, 2017). "MR-1-stably-transfected 239T cells were established to investigate the potential role of MR-1 in cell invasion and tumor progression." (PMID 21702971, 2011). "Furthermore, we observed that all the tumours with weak expression of Pax3::Foxo1 were significantly enriched in the MR2 subset compared with the MR1 subset (p = 0.015)." (PMID 39812007, 2025).
tumor (continued). "In addition, MAIT cells in the colon are activated by tumor cells presented through MR1, thereby negatively impacting the antitumor responses of NK cells and CD8+ T cells." (PMID 41179703, 2025). "Initial examination of these clusters/subsets revealed that all GEMM tumours in ML clusters corresponded to Pax3::Foxo1 in one of three lineages (Myf5, Myf6, and Pax3) while all tumours in MR1 corresponded to DNA alterations other than Pax3::Foxo1 in these same three lineages." (PMID 39812007, 2025). "On the other hand, some animal experiments show that tumor initiation, growth, and experimental lung metastasis were significantly reduced in Mr1 knockout mice, compared to wild-type animals, suggesting that MR1 expression promotes cancer at least in mice." (PMID 40362653, 2025). "In recent years, MR1 has held great promise as a target for TCR-mediated tumor immunotherapy." (PMID 39445059, 2024). "In this study, we have shown that the 7G5.TCR derived from the MC.7.G5 T-cell clone and other MR1-restricted TCRs with similar properties (e.g., tumor cell recognition and MR1 K43-dependence) robustly redirect T cells to kill cancer cells in the TCR-T format both in vitro and in vivo." (PMID 39445059, 2024). "Interestingly, 5-OP-RU and TLR9 agonist combination work independently of MHC class I related-1 molecule (MR1) expression in tumor cells." (PMID 37508372, 2023). "Thus, MAIT cells are capable of achieving tumor recognition and activation through alternative mechanisms other than detection of MR1-presented antigen." (PMID 35565395, 2022). "Although the reason for this discrepancy currently remains unclear, differences in the dynamics of MR1 shuttling between ER and the plasma membrane upon a 5-OP-RU challenge or putative ligand(s) present in the tumor milieu (TM) may be a key feature." (PMID 35379387, 2022). "Similarly, MR1 knockout mice exhibit tougher, resistance relative to the control mice, upon methylcholanthrene (a tumor-initiating reagent) inoculation." (PMID 36551916, 2022). "Accordingly, MAIT cells may be involved in the occurrence and development of malignant hematological tumors through MR1 molecules on monocytes or B cell-related tumor cells." (PMID 36052080, 2022). "This allows speculation that MR1 expressed by each different tumour cell type might present a peculiar variety of antigens." (PMID 34718585, 2022). "MAIT cells exist widely in various TMEs and can be activated by the MR1 of tumor cells via IL-17, thereby inhibiting the effector functions of NK cells and/or CD8+ T cells (including IFN-γ release and degranulation) to promote tumor initiation, proliferation, and metastasis." (PMID 35733919, 2022). "Although these MAIT-like lymphocytes showed similar global gene expression profiles to that of CB-MAIT cells, it remains unclear whether these MAIT-like lymphocytes retain anti-tumor specificity through MR1-recognition and effective tumor-killing cytotoxicity." (PMID 35565395, 2022). "Recently, it was suggested that MAIT cells could suppress NK cell functions in a mechanism that is dependent on IL-17 and MR1 expression by tumor cells, resulting in faster tumor growth and metastasis." (PMID 34298791, 2021). "Recent evidence has demonstrated that MR1 can also present other small molecule ligands, including drugs, nonmicrobial MR1 ligands and even undefined tumour‐associated ligands." (PMID 33624424, 2021). "Germline variants in MR1 may confer decreased OS by impacting the ability of MAIT cells and/or other MR1-restricted T-cells to slow tumor progression." (PMID 33919687, 2021). "Interestingly, another recent study found that tumor-derived antigen presentation by MR1 to conventional T cells resulted in significant anti-tumor activity." (PMID 34362900, 2021). "However, a recent study demonstrated a key MR1–MAIT cell axis controlling tumor growth and metastasis." (PMID 34298791, 2021).
tumor (continued). "In addition to these external antigens, MR1 can activate T cells through the presentation of tumor-derived proteins." (PMID 33948562, 2021). "We observed different levels of MR1 staining of the tumor cells in primary versus recurrent GBM, with 0 versus 1 patients showing no (−), 4 versus 2 patients showing low (+), 4 versus 10 patients showing medium (++), and 11 versus 6 showing high (+++) staining." (PMID 33948562, 2021). "However, cancer metabolite recognition by MR1-restricted T cells has also been demonstrated, indicating a role for MR1-dependent host tumour surveillance." (PMID 34377970, 2021). "CD1- and MR1-restricted T cells are not HLA-restricted and have the potential to serve as a unique source of universal TCR sequences to be broadly applicable in TCR-based ACT as their targets are presented by the monomorphic CD1 or MR1 molecules on a wide variety of tumor types." (PMID 33262761, 2020). "Furthermore, MAIT cells from healthy donors can efficiently lyse MR1 proficient tumor cells presenting microbial agonists such as 5-OP-RU, suggested as a potential strategy to harness the MAIT cell response therapeutically." (PMID 33013835, 2020). "Whether MAIT cells can recognize tumor neoantigens in the context of MR1 presentation and whether they can respond to tumor cells are important questions." (PMID 32053875, 2020). "Until now, little is known about MR1 distribution and it has yet to be elucidated whether MR1 expression on tumor cells could be important in MAIT cell activation." (PMID 30298063, 2018). "This approach highlights the possibility that selective MR1 agonists can enrich MAIT cell-mediated tumor immunity in MM and may also prove relevant in other tumors; however, in vivo models are essential to examine the stimulatory molecules to induce an anti-cancer effect of MAIT cells." (PMID 40746558, 2025). "Intriguingly, it appears that MR1 indeed may present endogenous and tumor-associated antigens to non-MAIT MR1-restricted T cells." (PMID 37020559, 2023). "Thus, whether the MR1 pathway of MAIT cells mediates protumor or anti-tumor effects is still inconclusive, and the role of MR1 in malignant hematological tumors still needs more research to be confirmed." (PMID 36052080, 2022). "Importantly, MR1T cells recognize and kill a diverse range of MR1-expressing tumor cells." (PMID 32411144, 2020). "MR1-restricted T cells might also be considered in tumor immunotherapy." (PMID 29963057, 2018). "Unknown candidate ligand: (i) Broad patient applicability via MR1 (limited-polymorphism); (ii) MR1 is upregulated in metabolically stressed/cancerous cells; (iii) MR1 ligand stability (e.g., 5-OP-RU) is limited; (iv) tumor-specific MR1 presentation not fully characterized." (PMID 40746558, 2025). "By recognizing MR1-presented metabolites, MAIT cells can directly target MR1-expressing tumor cells presenting vitamin-B-derived metabolites." (PMID 41148807, 2025). "The protein product of the gene MR1 (MHC class I-related molecule), is involved in antigen presentation to T cells, including tumor-related antigens." (PMID 33919687, 2021). "In these experiments, we also utilized a MSCV-cherry retroviral vector to overexpress MR1 on B16F10 cells (B16F10cherryMR1) and compared tumor growth to control B16F10 cells (B16F10cherry)." (PMID 34362900, 2021). "We therefore assessed B16F10 tumor metastasis in B6-MAITcast MR1 WT and B6-MAITcast MR1−/− mice in the context of NK cell depletion using anti-asialo GM-1 (αASGM1), after confirming that αASGM1 did not deplete MAIT cells." (PMID 34362900, 2021). "Similar results were achieved when B6-MAITcast MR1 WT mice were challenged with E0771 tumors, confirming the effectiveness of MAIT cell expansion in multiple tumor models." (PMID 34362900, 2021). "Self-reactive MR1-restricted MR1T cells were isolated and identified by their ability to recognize tumor cells in a TCR-mediated manner." (PMID 32411144, 2020).
tumor (continued). "Recent evidences revealed that tumor initiation and metastasis formation is reduced in mice knockout for MHC class I-related protein-1 (MR1), which is essential for MAIT development." (PMID 32265933, 2020). "Thus, MAIT’s MR1-specific cytotoxic activity may reach many cell types within a tumor, disrupting the integrity of the tumor stroma, vessels, and lymphoid tissues, and facilitating the dissemination of tumor cells beyond the tumor milieu." (PMID 32756356, 2020). "This pathway enables CAR–MAIT cells to maintain cytotoxicity even against MR1‐negative tumors, thus effectively combating tumor antigen escape." (PMID 41179703, 2025). "Validation of our approach led to the understanding that conserved SNPs present in MR1 can drive T-cell activation, in a highly MR1*04-specific manner, that is not exclusive to tumor cells." (PMID 39445059, 2024). "However, it is likely that MAIT cells are able to target tumor cells in a TCR-MR1 axis-independent manner, since ex vivo cultured MAIT cells not only suppressed MR1+ tumor cell lines in vitro but also eliminated MR1− tumor cells (unpublished data)." (PMID 36463401, 2023). "Taken together, these results suggest that although MAIT cells exhibit antitumor response upon activation by microbial metabolites 5-OP-RU, the tumor killing is not dependent on the tumor MR1 expression." (PMID 36463401, 2023). "As MR1 belongs to the MHC class I molecules and is a target of immunotherapeutic drugs, we believe that our data presents an opportunity to understand the relationship between organ specific tumor metabolism and drug efficacy in the metastatic setting." (PMID 38313277, 2023). "Although MR1 constrains the development and expansion of MAIT cells harboring TRAV1-2-TRAJ33 (J12 and J20 in human), other MR1-dependent T (MR1-T) cells, which expand upon coculture with tumor cells, exist." (PMID 36551916, 2022). "Such an MR1-independent anti-tumor immune response is of importance, given that not all tumors necessarily express MR1 on the surface or are induced to express it upon exposure to an agonist such as 5-OP-RU." (PMID 36551916, 2022). "In fact, it is now becoming more evident that MR1 could offer a sample of a cell’s metabolism to MR1T cells, thus recognizing alterations occurring during tumour transformation or other conditions of persistent cell stress." (PMID 34718585, 2022). "Although the involvement of TCR-mediated recognition of each tested tumour cell line was not investigated, these data confirmed previous data suggesting that the occurrence of MR1-presented antigens can be shared by several tumour cells." (PMID 34718585, 2022). "Having verified successful knockout of MR1 on B16F10 tumor cells, we observed that 5-OP-RU no longer exhibited an anti-tumor effect, thus confirming the requirement for tumor-derived MR1 expression in this antigen-pulsing model." (PMID 34362900, 2021). "A positive correlation to LH was found for LGR4 that regulates expression of estrogen receptor and MR1 that mediates tumor immune escape, whereas there was a negative correlation between LH and GIT2, implicated in aging and cellular senescence." (PMID 34758873, 2021). "Furthermore, following NK cell depletion B6-MAITcast MR1−/− and B6-MAITcast MR1 WT mice exhibited a similar metastatic burden following B16F10 tumor challenge, indicating that the enhanced protection exhibited by B6-MAITcast MR1−/− mice is NK cell dependent." (PMID 34362900, 2021). "Regulation of MR1 expression is not currently well described in healthy tissues or in tumor cells, and future therapies targeting MR1 will benefit from further understanding." (PMID 33805904, 2021). "Additional studies on MR1-restricted antigens and the TCR repertoire may provide new insights into tumor immunity and other diseases." (PMID 33185693, 2020). "In line with a previous report by our group, we also observed a high frequency of CD39+ CD8+ tumor-infiltrating lymphocytes (TILs) in CRC (tet-MR1-negative T cells)." (PMID 33205061, 2020).
tumor (continued). "MR1T cells showed preferential recognition of tumor cells and not of normal cells, even when the levels of expressed MR1 were physiologically very low." (PMID 29963057, 2018). "In conclusion, these data indicated that MR1T cells recognize MR1 complexed with ligands not derived from culture medium and present also in tumor cells grown in vivo." (PMID 28518056, 2017). "However, whether the availability and identities of MR1 ligands regulate the levels of MR1 expression and shape the impact of MAIT cells across different cancers remains largely unknown, making their role in tumor immunity an area of active investigation." (PMID 40746558, 2025). "It detects phosphoantigens resulting from mevalonate pathway dysregulation in tumor cells, while Vδ1+ (delta 1 subset of gamma delta T cells) subsets dominate mucosal sites and target non-classical MHC molecules, such as CD1 (family of glycoproteins) and MR1 (MHC class I-related protein 1)." (PMID 40872545, 2025). "While further efforts are needed to confirm the relevance of the MAIT TCR/MR1/5-OP-RU axis in the direct cytotoxicity of MAIT cells against tumors, molecular mechanisms that contribute to the discrepancy of MR1 upregulation between different tumor cell lines require further investigations." (PMID 36463401, 2023). "Furthermore, the reactivity of MR1T cells towards tumours and not healthy cells indicates tight regulation in the generation of self-antigens and in MR1 expression and antigen loading." (PMID 34718585, 2022). "Furthermore, nonMAIT, MR1-restricted T cells have recently been shown to recognize and kill several tumor cells in an MR1-dependent manner." (PMID 36052080, 2022). "Although the MR1-dependent tumour recognition was not confirmed in all instances, this study was in line with those in which recognition of a smaller number of tumour cell lines was investigated and confirmed that MR1T cells can also recognize antigens shared among different tumour cell lines." (PMID 34718585, 2022). "Regulation of MR1 expression is currently not well described in healthy tissues or tumor cells." (PMID 36052080, 2022). "However, no reduction in tumor metastases following 5-OP-RU pulsing was observed in B6-MAITcast MR1−/− mice, confirming the absolute requirement for MAIT cells in this protective effect." (PMID 34362900, 2021). "Furthermore, the number and fold-change of 5-OP-RU-pulsed tumor cell metastases were much lower than non-pulsed B16F10 tumors in B6-MAITcast MR1 WT mice and C57BL/6 WT mice." (PMID 34362900, 2021). "Interestingly, the observed T cell reactivity was donor-unrestricted, with multiple HLA-mismatched tumor cells recognized in an MR1-dependent manner, whilst not exerting allo-reactivity, making this T cell clone particularly interesting for immunotherapies." (PMID 33013835, 2020). "Indeed, changes in cellular metabolites, for example, during neoplastic transformation, could potentially interfere with MR1 trafficking and modulate MAIT cell function in the tumor microenvironment." (PMID 32341160, 2020). "However, MR1T cells, the atypical MR1-restricted T cells, have a predominant role in killing tumor cells while sparing noncancerous counterparts." (PMID 32756356, 2020). "Interestingly, CRISPR-Cas9 genome screening has introduced major histocompatibility complex, class I-related (MR1) protein as a tumor-specific target for non-conventional TCR T-cells." (PMID 32973401, 2020). "In the absence of defined tumor antigens binding to tumor-derived MR1, it is reasonable to speculate that MAIT cells may be regulated by microbial antigens and may be more frequent in tumors with a microbial presence." (PMID 32849557, 2020). "In addition, other atypical MR1 restricted T cells (not responding to 5-OP-RU) have been described, some reacting towards tumor cells such as “MR1T cells”, but more research is needed to unravel the precise nature and function of these cells." (PMID 32053875, 2020).